HHLA2 (HHLA2 member of B7 family)
Diseases named in the same sentence as HHLA2 in open-access papers (continued):
Sharing a sentence is not in itself a finding about the gene and the disease.
tumor (continued). "A co‐culture model of THP‐1 macrophages and NSCLC cells was conducted to investigate the impacts of tumor cell‐derived HHLA2 on THP‐1 macrophage polarization." (PMID 34152094, 2021). "Our results are in line with a previous study which found that tumor HHLA2 expression was significantly correlated with OS of NSCLC." (PMID 34181347, 2021). "Coexpression of these QIF markers in the tumor compartment was scarcely detected except for PD-L1 and HHLA2, which was observed in 69.6% of cases." (PMID 35145510, 2021). "Coexpression of these QIF markers in the tumor compartment was scarcely detected except for PD-L1 and HHLA2." (PMID 35145510, 2021). "While PD-L1 and HHLA2 had remarkable coexpression in the tumor subarea, other markers were infrequently coexpressed in this region." (PMID 35145510, 2021). "Among all tested tumors, KIRC showed the highest transcript level of HHLA2, and HHLA2 levels were significantly higher in tumor tissues than in matched normal samples, as evidenced by both TCGA and IHC data." (PMID 32509772, 2020). "HHLA2 showed significantly higher expression in tumor tissues than that of the matched normal samples in both cohort 1 (paired, n = 90) and cohort 2 (paired, n = 30)." (PMID 32509772, 2020). "First, we analyzed HHLA2 expression in KIRC tumors and matched normal tissues from TCGA dataset and found that HHLA2 expression is significantly higher expression in KIRC tumor tissues than in matched normal samples." (PMID 32509772, 2020). "Together, these results demonstrated that HHLA2 was highly expressed in the tumor sites, and that increased expression is positively correlated with OS of patients with KIRC." (PMID 32509772, 2020). "HHLA2 exhibited significantly higher expression in KIRC tumor tissues than in matched normal samples." (PMID 32509772, 2020). "Next, we investigated why HHLA2 overexpression in the KIRC tumor sites is correlated with good prognosis." (PMID 32509772, 2020). "This study aimed to investigate the prognostic impact of HHLA2/PD-L1 co-expression and its relationship with tumor-infiltrating lymphocytes (TILs)." (PMID 31959726, 2020). "In contrast to that in normal tissues, the protein expression of HHLA2 is widely observed in most of tumor specimens from the colon, breast, lung, thyroid, pancreas, ovary, liver, bladder, prostate, kidney, and esophagus, as well as in melanoma specimens." (PMID 32477326, 2020). "CD8 levels were significantly upregulated in tumor tissues of the HHLA2-high group compared with the HHLA2-low group (n = 250, P < 0.01)." (PMID 32509772, 2020). "HHLA2, a member of the B7 family, was reported to be involved in the immunosuppression of the tumor microenvironment by modulating human T cell function." (PMID 31777602, 2019). "The stained area was mostly in cytoplasm, on the membrane of tumor cells and the expression of HHLA2 was scarcely detected in para-tumor liver tissues, which were concordant with previous studies." (PMID 30885276, 2019). "Although HHLA2 can be induced on B cells and monocytes by IFN-γ and LPS, the mechanism of how tumor cells enhance HHLA2 expression remains to be further investigated." (PMID 30885276, 2019). "HHLA2 expression was associated with EGFR mutation status and high tumor infiltrating lymphocytes (TILs) density." (PMID 30885276, 2019). "Secondly, limited to the number of TMAs, PD-L1 expression as well as the correlations between typical subsets of tumor infiltrating immune cells and PD-L1, HHLA2 expression were only studied in our training cohort." (PMID 30885276, 2019). "Immunohistochemical analysis demonstrated that HHLA2 mRNA levels in blood specimens were weakly correlated with HHLA2 protein expression in primary tumor tissues (r = −0.258, P = 0.0283)." (PMID 29774123, 2018). "HHLA2 expression was inversely related with the depth of tumor invasion, distant metastasis, and stage of disease." (PMID 29774123, 2018).
tumor (continued). "In this study, we compared differences in HHLA2 expression between blood specimens and primary tumor tissues in each patient." (PMID 29774123, 2018). "Spearman’s rank test showed a weak linear relationship in HHLA2 expression between blood specimens and primary tumor tissues (r = −0.258, P = 0.0283)." (PMID 29774123, 2018). "Over 50% of tumors that expressed HHLA2 demonstrated an expression pattern with greater than 25% of tumor cells staining positive." (PMID 27531281, 2016). "Overall, HHLA2 expression was more prevalent than PD-L1 expression (56% vs. 25%, p = 0.003), and within tumor specimens a higher proportion of cells, greater than 25% of the tumor volume, stained positive for HHLA2 compared with PD-L1 (21.4% vs 0%, p < 0.001)." (PMID 27531281, 2016). "HHLA2 expression in HCC tissues correlated with c-Met phosphorylation, and HHLA2 could be detected in the serum of patients with high tumor HHLA2 levels." (PMID 40394703, 2025). "In vitro experiments showed that HHLA2 promotes PTC cell progression, indicating its function as a tumor promoter, thereby suggesting that targeting HHLA2 could represent a novel therapeutic approach for PTC." (PMID 40255615, 2025). "However, the dichotomy in HHLA2 expression between tumor cells and TAMs highlights the complexity of its role in tumor progression and immune modulation, with one study observing that HHLA2 expression in TAMs was correlated with poorer prognosis in PC." (PMID 40255615, 2025). "This implies that heightened HHLA2 expression could potentially occur in tissues beyond the tumor site." (PMID 40255615, 2025). "Given the widespread expression of HHLA2 in solid tumors, the KIR3DL3-HHLA2 pathway may be a key mechanism of tumor immune evasion." (PMID 40784895, 2025). "In addition, in MTC, there is evidence of a relationship between HHLA2 expression, tumor progression and diminished disease-free survival." (PMID 40255615, 2025). "A limitation is that we did not directly assess HHLA2’s impact on immune cell c-Met; therefore, further investigation is needed to fully elucidate the interplay between HHLA2, c-Met signaling on both tumor and immune cells, and the overall immune microenvironment." (PMID 40394703, 2025). "In addition to these factors involving the TME and intrinsic tumor biomolecular context, discrepancies in findings regarding HHLA2 expression as a prognostic factor in endocrine-related tumors can be attributed to several other potential factors." (PMID 40255615, 2025). "Immunohistochemistry revealed high HHLA2 expression in 53.2% of tumor tissues." (PMID 38786018, 2024). "Moreover, HHLA2 expression plays different roles in immunological cells and the tumor microenvironment." (PMID 38786018, 2024). "IHC revealed HHLA2 staining in tumor, stromal, and immune cells, and the median score of HHLA2 expression in the tumor compartment was significantly higher than in the stromal compartment (31.5% compared with 7.35%), indicating stronger HHLA2 expression in the tumors (p < 0.0001)." (PMID 38786018, 2024). "TNFRSF18 is involved in immune activation, promoting T cell proliferation and enhancing anti-tumor immune responses, while HHLA2 plays a role in immune checkpoint regulation, suppressing T cell activation and contributing to immune evasion in the tumor microenvironment." (PMID 38561648, 2024). "HHLA2-positive groups exhibited a larger maximum tumor dimension, higher lymphovascular invasion, and elevated risk of disease progression and all causes of death, while high HHLA2 expression corresponded strongly to the advanced TNM stage, higher Fuhrman grade, and necrosis, suggesting that." (PMID 38786018, 2024). "HHLA2 was reported to disrupt anti-tumor immunity and inhibit immune surveillance." (PMID 38553708, 2024).
tumor (continued). "Univariate Cox proportional regression analysis identified various risk factors for OS in the training cohort, including tumor number, size, differentiation, MVI, AFP, GGT, CD34, CD68, CD66b, Treg/CD8, CCR4-T, CCL17-T, CCL17-I, HHLA-2, CD73-T, and CCR4 + CD73 + cells." (PMID 38914802, 2024). "Importantly, HHLA2 silencing led to a smaller tumor size in vivo, reduced the viability of A549 and H1299 cells, and decreased Ki67 levels." (PMID 38786018, 2024). "IHC showed, as well, lower PD-L1 expression and TAM levels in tumor tissues of HHLA2 KD in mice." (PMID 38786018, 2024). "In conclusion, enhanced HHLA2 expression in RCC may promote immunological responses in the tumor environment, thus contributing to a better prognosis for patients, but this relationship is unclear." (PMID 38786018, 2024). "Additionally, the intensity of CD68+ TAM infiltration was elevated with increasing HHLA2 expression in both tumor and CK−CD8−CD68− area cells (p < 0.0001)." (PMID 38786018, 2024). "Moreover, they presented lower EdU incorporation in the EdU assay, indicating that cell proliferation and tumor growth were decreased in the event of HHLA2 overexpression." (PMID 38786018, 2024). "It has been reported that HHLA2 contributes to complex functions in the tumor microenvironment." (PMID 36982953, 2023). "Therefore, the negative correlation between protumor factors and HHLA2 is further evidence of the dual effect of HHLA2 on tumor development." (PMID 36982953, 2023). "Although HHLA2 has been established as a novel immune checkpoint molecule, its role in tumor progression and tumor immune evasion remains unclear." (PMID 36598731, 2023). "HHLA2 expression on tumor cells is progressively lost when cells are cultured over a 4 week period." (PMID 37891555, 2023). "Moreover, similar to the results with ccRCC nephrectomy specimens, HHLA2 expression on A498 was lost when tumor cells were cultured in vitro." (PMID 37891555, 2023). "Patients with high HHLA2 expression had better post-surgical survival and delayed tumor recurrence." (PMID 38144305, 2023). "Future studies could also examine the relationship between HHLA2 and CAFs in the stromal microenvironment, and whether CAFs induce tumor progression by modulating the immunosuppressive stromal microenvironment through the activation of s-HHLA2." (PMID 36598731, 2023). "This shows that some signal provided by the tumor microenvironment can induce HHLA2 in vivo." (PMID 37891555, 2023). "In addition, CD48, CTLA4, HHLA2, TNFSF9, and TNFSF15 were elevated in high-risk group, suggesting that the high-risk group are more likely to show immunosuppressive phenotype in tumor microenvironment." (PMID 37903974, 2023). "Second, it’s interesting that, based on our in vitro cellular investigation and in vivo tumor model study, we also demonstrated that overexpression of HHLA2 could significantly reverse the tumor inhibition mediated by METTL3 depletion." (PMID 35794583, 2022). "We found that HHLA2 is ubiquitously expressed in tumor cells." (PMID 36003385, 2022). "The expression of HHLA2 in each tumor was analyzed by using TCGA database." (PMID 36003385, 2022). "Blockade of both PD‐1 and HHLA2 in patients with ccRCC may be a more effective way to reverse tumor immune evasion." (PMID 35441741, 2022). "Furthermore, when the tumor advanced in terms of stage and grade, the expression level of HHLA2 increased." (PMID 35371079, 2022). "The subcutaneous transplantation tumor model was used to study whether HHLA2 overexpression could reverse the inhibition of tumor growth induced by METTL3 depletion." (PMID 35794583, 2022). "KIR3DL3, as the second receptor of HHLA2, is mainly expressed in terminal differentiation effector memory CD8+ T cells and CD56dim CD16+ NK cells, which mediates co-inhibition of CD8+ T cells and NK cells and induces HHLA2+ tumor tolerance against tumor killing." (PMID 36003385, 2022).
tumor (continued). "These opposing functions emphasized that the expression and distribution of HHLA2 and its receptor may determine the immune response in the tumor microenvironment, thereby influencing prognosis." (PMID 36618968, 2022). "The subcutaneous transplantation tumor model confirmed that HHLA2 overexpression could reverse the inhibition of tumor growth mediated by METTL3 depletion." (PMID 35794583, 2022). "It is speculated that the function of HHLA2 within the TME of PDAC may change as the tumor progresses." (PMID 36499340, 2022). "This suggests that HHLA2 expression may be responsible for tumor progression, and HHLA2 can give tumor survival advantage by inhibiting host anti-tumor immunity." (PMID 35287670, 2022). "In particular, most of the mRMR genes (n = 7) were obtained from the differential gene expression analysis (DEA) comparing normal tissues versus primary tumor samples, with a larger number of upregulated genes, including the mRMR genes HHLA2, LINC01732, SAA1, AL353637.1, and ZIC2." (PMID 35565241, 2022). "Moreover, data of normal tissues which was obtained from the GTEx database and data of tumor tissues which was obtained from TCGA were integrated for analyzing the differences in HHLA2 expression levels among 33 tumor types." (PMID 36003385, 2022). "Patients with the HHLA2+/PD-L1+ tumor phenotype may likely benefit from the dual blockade of PD-L1 and HHLA2 by immune-based drugs." (PMID 35145510, 2021). "Importantly, HHLA2 and PD-L1 coexpression on tumor cells independently predicted both worse LRFS and OS." (PMID 35145510, 2021). "Importantly, HHLA2 and PD-L1 coexpression on tumor cells independently predicted both worse local recurrence-free survival and overall survival." (PMID 35145510, 2021). "Thus, it indicates that high level of HHLA2 potentially plays an important role in tumour progression through immune suppression." (PMID 33962626, 2021). "Tumor immune evasion is one of the hallmarks of malignancy, and expression of the B7 family of ICPs Immune checkpoint molecules (PD-L1, PD-L2, B7-H3, B7x and HHLA2) is one mechanism of immune evasion by tumors." (PMID 34181347, 2021). "Given its emerging role of suppressing tumor immune responses with possible different immune evasion mechanisms from PD-1/PD-L1 pathways, there has been a great interest for exploration of HHLA2 as a therapeutic immune target." (PMID 34181347, 2021). "Importantly, tumoral HHLA2/PD-L1 coexpression in the tumor subregion independently influenced both LRFS and OS." (PMID 35145510, 2021). "Tumor HHLA2 and PD-L1 were positive in 80.0% and 86.0% of cases, respectively." (PMID 35145510, 2021). "Interestingly, multiple researchers have pointed to the double-edge sword properties of HHLA2 in different tumour tissues." (PMID 33962626, 2021). "HHLA2 was highly expressed in ccRCC tissues, which could function as a T-cell co-inhibitory factor to play an immunosuppressive effect, promoting tumor migration and invasion." (PMID 34537809, 2021). "HHLA2 is localized in both the cytoplasm and the membrane of tumor cells." (PMID 32477326, 2020). "In tumor sites, HHLA2 expression is positively correlated with survival time." (PMID 32509772, 2020). "Nevertheless, HHLA2 expression on tumor cells has also been reported to stimulate tumor angiogenesis through interactions with TMIGD2 on the endothelium, which may result in a poor prognosis." (PMID 32509772, 2020). "These opposing functions highlight that the expression and distribution of HHLA2 and its receptors may determine the reactions and immune responses in tumor microenvironment, further affecting the prognosis." (PMID 32509772, 2020). "Here, we analysed whether HHLA2 expression levels correlated with numbers of tumour-infiltrating CD8+ or Foxp3+ T cells." (PMID 32071413, 2020).
tumor (continued). "Evaluation of the correlation between tumor HHLA2 and clinicopathologic parameters in KIRC patients from two TAMs (n = 90 and n = 150) and 250 clinical samples revealed that tumor grade was correlated with HHLA2 expression in the validation 1 (n = 150) and 2 (n = 250) groups." (PMID 32509772, 2020). "In addition, expression of HHLA2 mRNA was detected in 23 out of 23 tested tumour tissues and, similar to protein expression, was strongly variable between individual patients." (PMID 32071413, 2020). "Furthermore, the univariate and multivariate Cox regression model using TCGA data revealed that age, tumor grade, clinical stage, and HHLA2 expression were independent prognostic factors for OS of patients with KIRC." (PMID 32509772, 2020). "It has been demonstrated that over-expression of HHLA2 in tumor microenvironment could dampen the T-cell mediated anti-tumor response, break the immune surveillance, and promote tumor immune invasion." (PMID 31015801, 2019). "Surprisingly, normal epithelial cells showed high expression of HHLA2 compared with tumor cells." (PMID 29774123, 2018). "Furthermore, HHLA2 expression was significantly correlated with the depth of tumor invasion (P = 0.0331), distant metastasis (P < 0.0001), and stage of disease (P = 0.0032)." (PMID 29774123, 2018). "Furthermore, we investigated the relationship between HHLA2 expression and tumor behavior to assess its clinical utility as a blood prognostic predictor." (PMID 29774123, 2018). "It is also possible that tumor cells may up-regulate HHLA2 expression as they form metastatic colonies in new tissues." (PMID 27531281, 2016). "Its association with CXCR4, HHLA2, and RAET1E points to a potential role in immune cell recruitment and NK/T‐cell activation, which could contribute to an altered immune landscape in the tumor microenvironment." (PMID 40952239, 2025). "Although no specific studies exist for HHLA2 in this situation, patients with high HHLA2 expression may be more sensitive to chemotherapy and have better responses to immunotherapy, indicating that HHLA2 might play a role in modulating the tumor’s response to chemotherapeutic agents." (PMID 40255615, 2025). "Moreover, the analysis revealed that HHLA2′s high expression was associated with poor OS regardless of its location within the tumor." (PMID 38731979, 2024). "Results of previous studies suggested that HHLA2 may serve as a new immune checkpoint molecule for the development tumor and participate in the process of tumor immune escape, and provide opportunities for the survival of tumor cell." (PMID 38762741, 2024). "We hypothesized that HHLA2 is over-expressed in PC and may facilitate the development of the tumor." (PMID 38762741, 2024). "Importantly, HHLA2 expression in Mo/Mφs was barely detectable in normal conditions, suggesting that it could be induced along with macrophage activation in the tumor microenvironment." (PMID 38786018, 2024). "HHLA2 expression in kidney and lung tumors has been shown to be non-overlapping with PD-L1 expression, suggesting that HHLA2 might mediate a mechanism of tumor immune evasion that is independent from PD-1." (PMID 37891555, 2023). "Thus, clarifying the mechanism of HHLA2 expression in the tumor and stromal cells in the TME may lead to new therapeutic approaches." (PMID 36598731, 2023). "Therefore, HHLA2 could be applied as an effective prognostic factor with diversified prognostic impacts according to tumor types." (PMID 36003385, 2022). "Hence, we speculated that the crosstalk between HHLA2-high expressing tumor cells and those immunosuppressive cells was mediated by those chemokines." (PMID 35371079, 2022). "Therefore, HHLA2 might affect malignant phenotypes such as tumour proliferation by exerting its tumour-intrinsic effects." (PMID 33962626, 2021). "Numerous studies revealed that overexpression of HHLA2 might be involved in tumor progression." (PMID 34152094, 2021).